SPARC (secreted protein acidic and cysteine rich)
Diseases named in the same sentence as SPARC in open-access papers (continued):
Sharing a sentence is not in itself a finding about the gene and the disease.
tumor (continued). "We also detected tumor and stromal cell SPARC expression in TNBC cytosols, and in patient‐derived xenografts and cell lines." (PMID 36346290, 2023). "SPARC plays an important role in the tumor evasion of immune surveillance by reducing anti-tumor PMN action." (PMID 37577749, 2023). "SPARC has an irreplaceable role to play in prognosis and cure for cancer by regulating the proliferation, migration, and apoptosis of tumor cells." (PMID 37577749, 2023). "In tumor treatment, functional nanomaterials have achieved certain results by manipulating SPARC-targeted therapy." (PMID 37577749, 2023). "Silencing SPARC resulted in inhibition of the M2 macrophage-mediated effects on tumor cell proliferation, migration, and angiogenesis." (PMID 37509139, 2023). "In the present study, we performed the complex analysis of mRNA and protein expression of crucial regulators of tumor angiogenesis and tumor progression, expressed by tumor-associated macrophages (TAMs): S100A4, SPP1 and SPARC." (PMID 36895491, 2023). "SPARC was localized in stromal cells, including CAFs, in the extracellular matrix and in some tumor cells." (PMID 36346290, 2023). "By quantitative proteomic analysis of clinical samples and cell lines, we found that decreased secreted protein acidic and rich in cysteine (SPARC) results in massive NETs formation and integrin α5β1 is the hub protein of NETs-tumor cell interaction." (PMID 37958984, 2023). "In the ovarian stroma containing malignant cells, particularly at the tumor–stroma interface in invasive tumors, elevated levels of SPARC mRNA and protein expression were found." (PMID 37577749, 2023). "In our in vivo study, the NIR fluorescence intensity of the tumor region was higher in the SPARC-positive U87MG tumor than in the U87MG-shSPARC tumor." (PMID 36614294, 2023). "An MTT assay revealed that all proteins except for SPARC (5 μg/ml) showed tumor-suppressing capability." (PMID 36943734, 2023). "The aim of this study was to evaluate SPARC expression in tumor and stromal cells, their prognostic value, and correlation with fibrosis, TAM infiltration, TIL density, PD‐L1 and PD‐1 levels in a large series of patients with non‐metastatic TNBC." (PMID 36346290, 2023). "The current mechanistic evidence from cell‐based studies suggests that the matricellular protein SPARC has a tumor‐promoting role in TNBC; however, data on the clinical relevance of SPARC expression/secretion by tumor and stromal cells in TNBC are limited." (PMID 36346290, 2023). "Myokines such as oncostatin M (OSM), secreted protein acidic rich in cysteine (SPARC), irisin, and decorin can directly restrain tumor development by blocking cell proliferation and migration and promoting tumor cell apoptosis." (PMID 37958310, 2023). "We found that the expression of pY14-caveolin-1 and SPARC protein was highly overlapped in tumor tissues treated with H2O2." (PMID 37528424, 2023). "In cancer, SPARC is mainly secreted by neighboring stromal cells, and to a lower extent by tumor cells." (PMID 36346290, 2023). "The authors observed endothelial cell death induced by SPARC overexpression by co-localization studies with TUNEL assay and an endothelial marker CD31 in a SPARC-overexpressed xenograft tumor model." (PMID 37509139, 2023). "In conclusion, the SPARC gene is involved in multiple processes of tumor development and progression in cancers including MESO." (PMID 37509139, 2023). "In cDNA array analysis, the expression of SPARC in tumor regions was senior compared with adjacent normal regions." (PMID 37577749, 2023). "In TNBC cells, SPARC stimulates their migration and invasion, and promotes MMP‐2 activation, thereby contributing to the proteolytic cascades associated with tumor invasion." (PMID 36346290, 2023). "In univariate analysis, tumor size, nodal status, adjuvant chemotherapy and SPARC expression in CAFs were correlated with RFS." (PMID 36346290, 2023).
tumor (continued). "We previously showed that stabilin-1+ macrophages mediate efficient clearance of matricellular protein SPARC and contribute to tumor progression." (PMID 36960065, 2023). "Previously, SPARC was reported to be involved in the regulation of multiple biological processes, including oncogenic and tumor suppressor properties." (PMID 35670884, 2022). "The subsequent tumor accumulation is presumably enhanced by the presence of albumin-binding proteins such as the “secreted protein acidic and rich in cysteine” (SPARC) found in the tumor microenvironment." (PMID 36145639, 2022). "The accumulation of Abraxane at the tumor site is also facilitated by SPARC (secreted protein, acidic and rich in cysteine), overexpressed in multiple types of tumors, including breast, prostate, gastric, lung, and kidney." (PMID 35057002, 2022). "SPARC is overexpressed in many solid tumors, and its in-situ expression decreased significantly in the tumor tissues treated with Bif@DOX-NPs, indicating its good anti-tumor efficacy." (PMID 35366890, 2022). "One of the important reasons for using albumin as an anti-tumor drug carrier is that albumin-binding proteins such as gp60 and SPARC are abundantly expressed in tumor cells." (PMID 36359230, 2022). "Although cytoplasmic staining was predominantly positive in the stroma cells in all NSCLC cases, we also observed weak SPARC staining in tumor cells across all three histological subtypes." (PMID 36452484, 2022). "To further confirm the possible beneficial role of the SPARC protein in BC patients, we collected BC tumor samples and analyzed the correlation between overall survival and SPARC expression." (PMID 36157225, 2022). "Tumors secrete cysteine-rich acidic proteins such as SPARC during growth that attract adherent albumin, thereby allowing drug translocation from the tissue interstitium into the tumor cells, eventually increasing the intra-tumoral accumulation of albumin NPs." (PMID 35366890, 2022). "SPARC regulates glioma growth by altering the tumor microenvironment and inhibiting tumor angiogenesis by suppression of VEGF expression and secretion." (PMID 35721704, 2022). "Copper binding protein SPARC is involved in tumor invasion and controlling copper ion levels by copper chelating agents seems to be a feasible method for tumor treatment." (PMID 36601107, 2022). "SPARC expression has been demonstrated to both promote and inhibit various forms of tumor cell activity." (PMID 35981080, 2022). "The expression of SPARC in tumors has been reported to be partly regulated through methylation in different tumor types." (PMID 36157225, 2022). "In all studies, SPARC was detected in tumor tissues, mesenchymal cells, or cancer cells by immunohistochemistry or quantitative real-time polymerase chain reaction." (PMID 35981080, 2022). "Comparison of the super-resolved image of SPARC with the H&E-stained image showed that the invasive tumor region overlapped substantially with the distribution of SPARC expression." (PMID 35260632, 2022). "Real-time PCR demonstrated that THC treatment significantly increased SPARC mRNA levels in MCF-7 xenograft tumor tissues, as well as protein levels confirmed by western blot." (PMID 36157225, 2022). "For example, the predicted expression patterns of SPARC, an invasion marker, highlighted a small tumor-invasion region difficult to identify using raw spatial transcriptome data alone because of a lack of measurements." (PMID 35260632, 2022). "High expressions of tumor cell genes COL5A2 and ITGAV and non-tumor cell genes SPARC and ACTA2 are both positively correlated with poor overall survival and disease-free survival in MESO cohort." (PMID 35046456, 2022). "Other researchers have identified abnormal methylation of SPARC in some tumor cell lines and that SPARC methylation induces gene silencing and inhibition of tumor activity, whereas demethylating agents can change methylation status and restore gene expression." (PMID 35981080, 2022).
tumor (continued). "Then, albumin nanoparticles enter the tumor interstitium and bind to SPARC proteins, releasing the entrapped drug." (PMID 35267507, 2022). "Most of these genes were tumor cell metastasis-associated genes such as TNC, PLAU, PDPN, SPARC, LUM, and especially SNAI2 (Zinc finger protein SLUG transcription factor)." (PMID 35742914, 2022). "High level of SPARC expression enhanced tumor invasion and metastasis, leading to a poor prognosis of patients." (PMID 35211625, 2022). "SPARC has been shown to modulate the mitogenic activity in normal endothelial cells in a dose-dependent manner and play dual roles in tumor angiogenesis and tumor extravasation and mediate permeability that is related to endothelial barrier function." (PMID 35721704, 2022). "SPARC is linked to the prognosis of HCC and can increase the proliferation and migration of tumor cells." (PMID 35981080, 2022). "For SPARC, the mean expression in tumor stroma was 14.24% ± 0.65 positive cells, with similar proportions among histotypes." (PMID 36452484, 2022). "Some myokines, such as irisin and secreted protein acidic rich in cysteine (SPARC), are produced by exercise and are reported to have roles in suppressing tumor growth and improving mortality for several cancers." (PMID 35683568, 2022). "It has been supposed that the tumor increase uptake of nab-paclitaxel (Abraxane®) occurs by this SPARC mediated pathway." (PMID 36230578, 2022). "In the tumor microenvironment, SPARC affects tumor growth, angiogenesis, and extracellular matrix deposition." (PMID 34209679, 2021). "In conclusion, in the primary cohort of MPM patients including long‐term survivors, high FAP and SPARC expression in stromal cells and high PDGFRB expression in tumor cells were associated with shorter survival." (PMID 33955203, 2021). "Concomitant SPARC up-regulation and radiation restricts tumor growth and angiogenesis by down-regulating VEGF-A via miR-410." (PMID 33718173, 2021). "In the tumor stroma, the IHC expression of SPARC and COL1A1 was significantly higher in the group with BM than that in the group without BM (p < 0.001 for both)." (PMID 34503278, 2021). "SPARC is normally expressed by stromal cells, showing either tumor suppressor or pro-oncogenic functions according to different types of cancer." (PMID 33800494, 2021). "SPARC has been shown to play significant roles in tumorigenesis, altering cancer cell activity and the tumour’s microenvironment, modulating cell growth, apoptosis, adhesion migration and invasion, regulating ECM and the activity of matrix metalloproteinases." (PMID 34205668, 2021). "In this study, we have shown that high FAP and SPARC expression in tumor stroma and high PDGFRB expression in tumor cells are associated with shorter survival in MPM patients in univariate analysis." (PMID 33955203, 2021). "Of the investigated fibroblast markers, high expression of FAP and SPARC in tumor stroma and high expression of PDGFRB in MPM tumor cells were associated with shorter survival." (PMID 33955203, 2021). "Nevertheless, the role of SPARC in tumor ECM is still controversial and is probably explained by the wide range of functions attributed to this particular protein." (PMID 33946660, 2021). "In contrast, the high SPARC expression showed a correlation with the highly aggressive tumor phenotype, through promoting tumor cell survival, proliferation, and invasion, such as glioma and melanoma." (PMID 34912848, 2021). "SPARC is involved in extracellular matrix synthesis and changes to cell shape, which can promote tumor cell invasion." (PMID 34638363, 2021). "The IHC analysis revealed an increased level of the SPARC protein in LIHC tissues compared to adjacent non-tumor tissues." (PMID 34912848, 2021). "TAM-derived Secreted Protein Acidic and Rich in Cysteine (SPARC) enhances tumor extracellular matrix deposition and interaction." (PMID 34771482, 2021).
tumor (continued). "Secreted protein acidic and rich in cysteine (SPARC) has a crucial role in the transport of nab-paclitaxel to a tumor." (PMID 34094924, 2021). "While macrophage infiltration was unaffected and M2 activation was mildly increased upon TGF-β inactivation in SPARC-/- mice, the increase in T reg cells was abrogated resulting in reduced tumor progression and survival." (PMID 33466303, 2021). "The IHC analysis showed an increased level of SPARC in LIHC tissues compared to adjacent non-tumor tissues." (PMID 34912848, 2021). "Of note, an association between increased SPARC expression and decreased tumor proliferation was found, but on the other hand, SPARC was shown to induce migration of GBM cells." (PMID 34681783, 2021). "Myokines, such as IL-6, irisin/FNDC5, decorin, oncostatin M (OSM), and secreted protein acidic and rich in cysteine (SPARC), have shown the potential of a direct tumor-suppressive effect in different cancer cell lines, including PCa." (PMID 34595123, 2021). "Collected data indicate that SPARC can be expressed by both cancer cells and stromal cells, especially TAMs, and realize its anti-tumor activity by inhibiting angiogenesis and decreasing cancer cell invasion and metastatic spread." (PMID 34209679, 2021). "First, the SPARC expression has been found to be either increased or decreased in different tumor types." (PMID 34912848, 2021). "First, based on TCGA and GEO databases, we found the mRNA expression levels of SPARC were increased in LIHC tumor tissues compared to non-tumor tissues." (PMID 34912848, 2021). "Downregulating the expression of SPARC can reduce the migration and invasion of tumor cells in ESCC." (PMID 34456964, 2021). "Albumin-bound formulation reduces tumor stroma via synergy between albumin and SPARC, thereby affecting the tumor microenvironment." (PMID 34094924, 2021). "SPARC can serve as a therapeutic target in ESCC since the high expression of SPARC can predict tumor prognosis, which was consistent with our findings." (PMID 34456964, 2021). "It was proposed that M2 macrophages can coordinate extracellular matrix remodeling, angiogenesis, and tumor progression by regulating SPARC extracellular concentration via stabilin-1-mediated endocytosis of SPARC." (PMID 34209679, 2021). "SPARC was consistently upregulated in the tumor stroma as compared to the normal stroma in each of these datasets (p 9A, 9B and 9C), underscoring its potential to contribute to collagen deposition in the tumor microenvironment." (PMID 33534863, 2021). "SPARC has also been found to be expressed in the margin between the primary tumour and the surrounding microenvironment (stroma cells) in primary and regional metastatic oral tongue squamous cell carcinomas, suggesting its role in invasion and metastasis." (PMID 34205668, 2021). "Given its vast variety of functions, SPARC has been reported to be a tumor promoter and suppressor depending on the type of cancer." (PMID 33466303, 2021). "SPARC is highly expressed in the tumor stroma, principally in peritumoral fibroblasts, and its expression (mainly associated with collagen and vitronectin) has been associated with poorer prognosis." (PMID 33946660, 2021). "Meanwhile, nab-paclitaxel, a nanoparticle form of paclitaxel, is known to deplete tumour stroma through interaction between albumin and SPARC." (PMID 34336679, 2021). "The IHC analysis of tissue microarray showed an increased level of the SPARC protein in LIHC tumor tissues compared to adjacent non-tumor tissues." (PMID 34912848, 2021). "It is also known that the secreted protein acidic and rich in cysteine (SPARC), an albumin-binding protein, can sequester albumin in tumor stroma and contribute to the tumor-specific uptake of albumin." (PMID 33114661, 2020).
tumor (continued). "Nab-PTX is associated with increased uptake by utilising the endogenous albumin pathways of gp60- and Cav-1-mediated endovascular transcytosis and binding between albumin and SPARC, which enables the drug to more thoroughly permeate the tumour." (PMID 32532230, 2020). "Cancers such as ovarian and pancreatic cancer express high levels of secreted protein acidic and rich in cysteine (SPARC), an albumin-binding 42-kDa matricellular glycoprotein whose expression in tumor interstitium correlates inversely with overall survival." (PMID 31858848, 2020). "In vivo injection of circ‐MALAT1 overexpressed cells (circ‐MALAT1 O/E) led to a larger tumor size, a higher tumor weight and a faster tumor growth rate than that of control cells (Vector and circ‐SPARC O/E)." (PMID 32099751, 2020). "In conclusion, M2-derived SPARC is an important protective factor in tumour region inhibition of tumour progression." (PMID 32226513, 2020). "In vivo experiments showed that SPARC overexpression can significantly reduce the role of M2 in promoting tumour growth (P<0.05)." (PMID 32226513, 2020). "Our findings show that HSA–CDDP has the potential to be a novel therapeutic agent for SPARC-expressing tumors, enhancing the tumor targeting effect by HSA and reducing the nephrotoxicity of CDDP." (PMID 33114661, 2020). "It’s worth noting that the influence of SPARC on tumor progression depended on the initiating cell type, tumor stage and context of the microenvironment." (PMID 33240930, 2020). "The SPARC immunoreactivity in tumor cells was observed only in the cytoplasm/cellular membrane of one case out of 21 NSCLCs (about 5%) having adenocarcinoma histology." (PMID 32580473, 2020). "SPARC is a 43 kDa secretory matricellular glycoprotein that has multiple biological functions, including tumor-suppressing activity, cell differentiation, and cell adhesion in several organs and cell types." (PMID 33019579, 2020). "We first evaluated the effect of downregulation of SPARC expression on the ability of tumor cell migration and invasion." (PMID 31897236, 2020). "In this study, the HSA–CDDP conjugate examined exhibited SPARC-dependent HSA-mediated tumor accumulation in a U87MG xenograft mouse model." (PMID 33114661, 2020). "The results illustrated that M2 SPARC overexpression can reduce M2-mediated resistance and apoptosis resistance of tumour cells." (PMID 32226513, 2020). "In order to verify the roles of SPARC in these behaviours, tumour cells were co-cultured with SPARC-regulated M2 or cultured in conditioned medium." (PMID 32226513, 2020). "In order to verify the effect of SPARC overexpression in M2 on the macrophage-mediated malignant tumour phenotype, we first needed to construct the M2 cell model and the regulated SPARC expression M2 cell model." (PMID 32226513, 2020). "The protein-NP complexes were purified by ultracentrifugation and assayed by dot blot analysis, which revealed protein-protein interactions between SPARC and Pt NPs, suggesting that SPARC plays a key role in tumor targeting of the Pt NPs." (PMID 31992692, 2020). "Another copper-dependent protein involved in promoting tumor metastasis and invasion is the Secreted Protein Acidic and Rich in Cysteine (SPARC)." (PMID 32041110, 2020). "There are two possible explanations for this: First, it can be postulated from the characteristics of SPARC, which is a secreted form of protein from tumor cells." (PMID 33114661, 2020). "Secondly, the mechanisms of regulation of SPARC expression and functions in the different cell types and SPARC expression exhibits distinctive compartmentalization with differential effects on tumor and stromal cell differentiation and plasticity." (PMID 32580473, 2020). "As reported, SPARC was shown to promote the proliferation, and migration of tumor cells and correlate with the prognosis of HCC." (PMID 32670867, 2020).